MLST8 (MTOR associated protein MLST8)
Diseases named in the same sentence as MLST8 in open-access papers (continued):
Sharing a sentence is not in itself a finding about the gene and the disease.
tumor (continued). "Moreover, transcripts relevant for cell division were regulated in Apoe−/−Neil3−/− cells, including upregulation of Zcchc2, which is reported to suppress tumorigenesis, and downregulation of Mlst8, deletion of which has been found to decrease tumor cell proliferation." (PMID 35079641, 2022). "Targeting mTORC2 signaling by deletion of MLST8 reduced glycolysis and limited extracellular lactate levels of LUSC tumor cells both in vitro and in vivo, while also reducing tumor growth in mice." (PMID 40640525, 2025). "The C2-tumor cluster had high autophagy (ATG5, MAP1LC3B), high plasticity (SOX4, CD164) and low mTORC1 activity (RPS6, MLST8), characteristics of early paligenosis (stages 1-2)." (PMID 36788228, 2023). "We found that BP can repress the mTOR pathway by downregulating MLST8 and EIF4EBP1 to inhibit AML cell proliferation and in vivo tumor growth." (PMID 35579750, 2022). "Reintroduction of CCT4 or mLST8 expression in YB-1–knockdown GSCWL1 and GSC456 cells reactivated mTOR signaling and partially rescued cell proliferation, tumor-sphere formation, and GSC self-renewal." (PMID 35239512, 2022). "Upregulated mLST8 induces phosphorylation of 4E-BP1, thereby stimulating cap-dependent translation of genes involved in cell growth and ultimately promoting of tumor progression." (PMID 25906254, 2015). "However, anti-VISTA does not affect tumor outgrowth in Mlst8-KO tumors, validating that VISTA and PSGL-1 function downstream of mTORC2." (PMID 40640525, 2025). "We found that mLST8 is upregulated in some human cancer tissues and cells, and that upregulated mLST8 promotes mTORC1/2 formation and induces activation of AKT and phosphorylation of 4E-BP1, resulting in promotion of tumor growth as well as invasive potential of cancer cells." (PMID 25906254, 2015).
cancer (18 papers, 2015 to 2026). A tumor composed of atypical neoplastic, often pleomorphic cells that invade other tissues. "Because the ability to form focal contacts is functionally linked to invasiveness of cancer cells, we examined the effect of mLST8-KD on in vitro invasive activity of HCT116 cells using a Matrigel-based chamber assay." (PMID 25906254, 2015). "On the other hand, several mutations in the mLST8 gene have recently been identified in cancer patients based on information in the Cosmic and CBio cancer genome databases." (PMID 25906254, 2015). "In this context, a recent paper investigated the role of mLST8 in a panel of normal and cancer cells showing that mLST8 loss, or even a single pair of mutations affecting mTOR binding, completely impaired mTOR association with mTORC2 cofactors RICTOR and SIN1 without affecting mTORC1." (PMID 40136688, 2025). "Our findings provide the first evidence that mLST8 is upregulated in a subset of human cancers; however, the molecular mechanisms underlying mLST8 upregulation are currently unknown." (PMID 25906254, 2015). "Given the central role of the mTOR/PI3K/Akt signaling axis in regulating autophagy and cancer in general, we examined the effects of these two compounds on the expression of the mTOR pathway regulator GβL/mLST8." (PMID 41155718, 2025). "But in addition, we also observed a strong correlation between TELO2 and RAPTOR (in nine out of 10 cancer types), mLST8 (in 10 out of 10 cancer types), mTOR, and RUVBL2 (in five out of 10 cancer types)." (PMID 40653822, 2025). "A recent study in a panel of normal and cancer cells showed that mLST8 acts as a scaffold protein for assembly and activity of mTORC2." (PMID 36435842, 2022). "The model prediction is consistent with previous findings that MLST8 is upregulated in several cancer types." (PMID 34529665, 2021). "To examine this further, we interrogated the alteration profiles of MLST8 in cancer patients from The Cancer Genome Atlas (TCGA)." (PMID 34529665, 2021). "Together, these findings highlight the potential of targeting MLST8 as an anti-cancer therapeutic strategy, which is currently under investigation." (PMID 34529665, 2021). "SIN1 and MLST8 are both subunits of mTORC1 and mTORC2 and participated in cancer cell migration and invasion." (PMID 34671559, 2021). "Overall, these results suggest that STAT3‐driven MLST8 gene expression regulates cap‐dependent translation through 4E‐BP1 phosphorylation in cancer cells." (PMID 32495998, 2020). "Overall, we suggest that mLST8 constitutes a potential target for cancer therapy as a cross‐road between STAT3 and the mTOR pathway." (PMID 32495998, 2020). "In this study, we showed that mLST8 knockdown induces dissociation of mTORC1/2 complexes in cancer cells." (PMID 25906254, 2015). "To examine the functional relevance of mLST8 to human cancers, we first analyzed expression levels of mLST8 protein in human colorectal primary tumors." (PMID 25906254, 2015). "By contrast, mLST8 knockdown in cancer cells led to reduction in formation of mTORC1/2 and phosphorylation of AKT and 4E-BP1, consistent with the results of a previous study." (PMID 25906254, 2015). "Because, in most solid tumors, the upregulation of GOLPH3 is associated with the enhanced activation of both mTORC1 and mTORC2, it will be important to further dissect the potential interplay of GOLPH3 with mLST8 in mTORC2 signaling in a broad set of cancer contexts." (PMID 40136688, 2025). "In cultured human cancer cells, depletion of GβL/mLST8 has been shown to impair mTORC1 signaling, suggesting that GβL/mLST8 may have a role in cancer via modulating mTORC1/C2 complexes’ function." (PMID 41155718, 2025). "Rictor and mTOR are prevalently observed in cancer, while mutations in mSin1, mLST8 and Raptor are not common in human cancers." (PMID 36539659, 2022). "We suggest that the STAT3/mLST8/4E‐BP1 signal pathway might be a valuable target for cancer therapy." (PMID 32495998, 2020).
cancer (continued). "STAT3 induces the expression of multiple genes related to cancer cell growth and survival, and also could activate cap‐dependent translation through MLST8 expression, further promoting cancer cell proliferation." (PMID 32495998, 2020). "Moreover, mLST8 knock down induces dissociation of mTORC1/2 complexes in cancer cells and significantly suppresses both mTOR complexes formation, thereby leading to a new role of mLST8 even in mTORC1." (PMID 29351204, 2018). "Further analyses of mLST8-mediated regulation of mTOR pathways may provide new targets for therapeutic intervention in a wide variety of human cancers." (PMID 25906254, 2015). "In this context, mLST8 may play distinct roles in normal and cancer cells, depending upon its expression levels." (PMID 25906254, 2015). "Also, the contribution of mLST8 to carcinogenesis and/or progression of human cancers, particularly those in which mTOR pathways are deregulated, remains uncharacterized." (PMID 25906254, 2015). "Western-blot analysis revealed a marked upregulation of mLST8 in all cancer cell lines tested." (PMID 25906254, 2015). "The distinct functions of mTOR in cancer and normal cells may be due to structural changes in mTOR complexes that are dependent on mLST8 levels." (PMID 25906254, 2015). "Previous studies have shown that upregulation of mLST8 induces the activation of both mTORC1 and mTORC2 in multiple cell types, simultaneously leading to deficits in melanin biosynthesis, melanosome development, and metabolic abnormalities in cancer and skin pigmentation diseases." (PMID 39957408, 2025). "RPTOR, mechanistic target of rapamycin kinase and MTOR associated protein (mTOR), LST8 homolog (MLST8) constitute the core subunits of the mammalian TORC1 complex which play an important role in controlling cell growth, survival and metabolism and is often deregulated in cancer." (PMID 29933410, 2018). "Database synthesis corroborated disease associations involving MTOR and its partners (e.g., TSC2, RICTOR, RPTOR, MLST8, AKT1 across selected carcinomas)." (PMID 41300706, 2025). "mTORC1 is composed of mTOR, regulatory-associated protein of mTOR (Raptor), mammalian LST8/G-protein β-subunit-like protein (mLST8/GβL) and the PRAS40 and DEPTOR partners and is a master regulator of protein synthesis that couples nutrient sensing to cell growth and cancer cell survival." (PMID 29383126, 2017). "RPTOR, mTOR, and MLST8 constitute the core subunits of the mammalian TORC1 (mTORC1) complex which play a major role in the control of cell growth and metabolism and is often deregulated in cancer." (PMID 27799065, 2016). "mLST8 knockdown reduced mTORC2-mediated phosphorylation of AKT in both cancer and normal cells, whereas it potently inhibited mTORC1-mediated phosphorylation of 4E-BP1 specifically in cancer cells." (PMID 25906254, 2015). "Upregulated mLST8 is required for activation and assembly of both mTORC1 and mTORC2 in cancer cells, although perturbation of mLST8 does not affect proliferation of normal cells." (PMID 25906254, 2015). "We have demonstrated that STAT3 acts as a trans‐acting factor for MLST8 gene expression and the protein level of mLST8, a core component of mechanistic target of rapamycin complex 1 and 2, positively regulates cap‐dependent translation through 4E‐BP1 phosphorylation in cancer cells." (PMID 32495998, 2020). "However, in cancer cells such as ACHN cells, in which eIF4B plays an important role, it is possible to stimulate cell growth by regulating cap‐dependent translation through the expression of eIF4B and mLST8 by STAT3." (PMID 32495998, 2020). "Overexpression of mLST8 also promoted colony-forming activity in non-transformed human keratinocyte HaCaT cells, although the colony-forming activity in these cells was substantially weaker than those in cancer cells." (PMID 25906254, 2015).
infection (6 papers, 2017 to 2025). The state of being infected such as from the introduction of a foreign agent such as serum, vaccine, antigenic substance or organism. "Further investigation of the TGEV viral titers in infected mLST8 KO cells at 12, 24, and 36 hours post-infection revealed that the viral titers of mLST8-KO cells were lower than those of WT cells at different time points." (PMID 37377422, 2023). "Intracellular +vRNA and −vRNA copies at 4 hpi (hour post infection) were increased in WT cells, while in mLST8 KO cells, the production of +vRNA and −vRNA was significantly inhibited." (PMID 37377422, 2023). "Confocal microscopy showed that the synthesis of double-stranded RNA (dsRNA), a marker of the TGEV RNA genome, was inhibited in mLST8 KO cells at 3 hours post-TGEV infection." (PMID 37377422, 2023). "TGEV RNA replication was significantly decreased in the mLST8 KO cells after infection at an multiplicity of infection (MOI) of 0.01." (PMID 37377422, 2023).
MLST8 also shares sentences with these, for which no sentence is quoted: lung carcinoma (2 papers); Obesity (2); cervical cancer (1); childhood ovarian dysgerminoma (1); gastric adenocarcinoma (1); gastric cancer (1); hematological disease (1); Hepatic steatosis (1); Huntington disease (1); Hyperglycemia (1); hyperlipidemia (1); Insulin resistance (1); leukemia (1); pancreatic cancer (1); parasitic infections (1); prostate tumors (1); renal carcinoma (1); sarcoidosis (1).